INS (insulin)
Diseases named in the same sentence as INS in open-access papers (continued):
Sharing a sentence is not in itself a finding about the gene and the disease.
Insulin resistance (continued). "Because the hyperinsulinemic–euglycemic insulin clamp technique, a gold standard method for quantifying the degree of insulin resistance, is difficult to apply in clinical practice, several indices derived from the OGTT have been evaluated." (PMID 24587359, 2014). "Unless subjects with insulin resistance produce great amounts of insulin to compensate for its effects, they will surely develop hyperglycemia and diabetes." (PMID 24741627, 2014). "Among healthy individuals and MS patients significant differences were observed in body weight, body-mass index, waist-circumference, levels of insulin, indices of insulin resistance, and levels of HDL-cholesterol, LDL-cholesterol and total triglycerides." (PMID 25243022, 2014). "In the presence of a severe insulin resistance, a disproportionate amount is secreted with a high percentage of immature forms of insulin being released into circulation, with a different half-life and action." (PMID 24741627, 2014). "Insulin resistance and the failure of insulin secretion from pancreatic β-cells are particularly critical for obesity-induced type 2 diabetes." (PMID 24705496, 2014). "4-PBA and TUDCA were demonstrated to improve insulin signaling and glucose homeostasis in human obese subjects characterized by insulin-resistance, and improved insulin sensitivity in obese subjects." (PMID 25352831, 2014). "Subjects in any of these three pre-diabetic states have moderate to severe insulin resistance, impaired insulin secretion and/or insulin sensitivity, and each state has distinct pathophysiologic etiologies and risks of developing into T2D." (PMID 25342083, 2014). "Insulin resistance is defined clinically as the inability of insulin to increase cellular glucose uptake and utilization, thereby leading to compensatory and chronic hyperinsulinemia." (PMID 24911052, 2014). "We have previously shown that blunting insulin signaling can actually prevent the HFD-induced insulin resistance/hyperinsulinemia." (PMID 24741073, 2014). "While insulin typically promotes glucose uptake as well as lipogenesis, insulin resistance describes resistance against the ability of insulin to trigger glucose uptake in liver, muscle, and adipose tissue." (PMID 25371775, 2014). "Visceral adipose tissue is a key endocrine organ involved in the regulation of insulin action and an important component in the development of insulin resistance." (PMID 24819750, 2014). "In lean individuals with normal insulin sensitivity and people with insulin resistance, African-Americans have significantly lower apoCIII levels than whites." (PMID 25553059, 2014). "In this study, we investigated prospectively the incidence of GDM and GIGT in Chinese pregnant women and analyzed insulin resistance as well as insulin secretion indexes and blood lipid correlations with glucose intolerance during pregnancy." (PMID 25674108, 2014). "Adolescents with hepatic steatosis (>5% by MRS) had increased ALT (P = 0.021), AST (P < 0.001), fasting insulin (P = 0.010), and insulin resistance as assessed by HOMA-IR (P = 0.013) compared with obese control adolescents." (PMID 25328713, 2014). "When insulin resistance occurs, the insulin signaling pathways of cells have a reduced ability to respond to the action of the hormone insulin." (PMID 25187806, 2014). "Other studies have reported positive associations of irisin with nutritional markers such as BMI, fat mass, IGF-1 and insulin, and with markers of the metabolic syndrome such as higher blood pressure, insulin resistance and lipid levels." (PMID 24926783, 2014). "Apart from decreased (relative) insulin secretion by the β cells, peripheral insulin resistance related to poor diet, physical inactivity, increased abdominal fat mass, and decreased lean body mass contribute to the deterioration of glucose metabolism." (PMID 25250626, 2014).
Insulin resistance (continued). "The effects of UDCA were comparable to fenofibrate with relatively better effects regarding serum insulin and insulin resistance index." (PMID 25202970, 2014). "Insulin resistance, a major abnormality underlying type 2 diabetes mellitus (T2DM) and obesity, is defined as the pathophysiological condition of reduced insulin responsiveness in liver, muscle, and adipose tissue." (PMID 24799887, 2014). "In males, mean levels of insulin, glucose, and Homeostasis Model Assessment of Insulin Resistance (HOMA-IR) were higher in the DD and DC groups than in the CC group." (PMID 24427280, 2014). "The main aim of this analysis was to evaluate the associations between hypoxemia, oxidative stress and inflammatory biomarkers with glucose, insulin and indices of insulin resistance." (PMID 24733551, 2014). "The Homeostatic model assessment (HOMA) is a secondary measure of insulin resistance based on fasting plasma glucose and fasting insulin that has been validated against the hyperinsulinemic euglycemic clamp." (PMID 31667162, 2014). "According to the repeated measurements, there were significant differences in weight (p=0.01), waist circumference (p=0.004), hip circumference (p=0.000), BMI (p=0.01), plasma insulin (p=0.002), and insulin resistance (p=0.004) within the groups over time." (PMID 25560330, 2014). "Taken together, LBP, as an inhibitor of JNK, results in marked improvement of insulin sensitivity in mouse models of HFD-induced insulin resistance." (PMID 25045414, 2014). "Recent data confirm that chronic elevation of intracellular ROS levels in adipocytes subsequent to mitochondrial dysfunction results in insulin resistance through attenuation of insulin signaling." (PMID 25143800, 2014). "If insulin resistance is inadequately compensated for due to insufficient increases in insulin secretion, hyperglycemia will occur." (PMID 24843074, 2014). "In patients with similar levels of insulin resistance and hyperglycemia, DM-NAFLD was associated with higher serum insulin levels than T2DM alone." (PMID 24397589, 2014). "The pathogenesis of type 2 diabetes is characterized by a combination of impaired insulin secretion from pancreatic β-cells and insulin resistance." (PMID 25272231, 2014). "To test the impact of insulin on browning in vivo, we employed established mouse models of insulin deficiency (streptozotocin (STZ) induced β-cell ablation) and insulin resistance (high fat diet (HFD) induced obesity)." (PMID 25313899, 2014). "In the high fat diet (HFD) fed animals exhibiting hyperinsulinemia and insulin resistance, CL treatment resulted in decreased body fat mass and reduced serum insulin as it did in control (LFD fed) animals." (PMID 25313899, 2014). "Previous studies have shown that impairment in insulin signaling is a major component of skeletal muscle insulin resistance." (PMID 25197650, 2014). "Fasting plasma glucose, fasting insulin, homeostasis model assessment for insulin resistance (HOMA-IR), and glycated hemoglobin (HbA1c%) were collected both prior to and following pioglitazone treatment." (PMID 25405601, 2014). "JNK is activated by extracellular signals such as cytokines and fatty acids and its importance on insulin resistance is demonstrated in JNK knock‐out mice which maintain normal insulin signaling function IRS‐1 serine phosphorylation during obesity." (PMID 24819750, 2014). "Lipids mediate insulin resistance in skeletal muscle via an ill-defined mechanism; however, promoting the rate of fatty acid oxidation in skeletal muscle has been proposed to affect insulin sensitivity in this tissue." (PMID 25152047, 2014). "In obese mice, fasting insulin levels were twice that of normal mice and fasting C-peptide was also elevated, reflecting insulin resistance." (PMID 24533136, 2014). "The pregnancy-related insulin resistance mainly occurs after the second trimester when insulin requirements are higher." (PMID 25215961, 2014).
Insulin resistance (continued). "Previous in vitro studies in our laboratory demonstrated that SJW inhibited adipogenesis, induced insulin resistance, and inhibited insulin-stimulated glucose uptake in mouse and human fat cells." (PMID 25136373, 2014). "To explore the effects of oral gavage administration of P. gingivalis on insulin resistance, we performed glucose and insulin tolerance tests." (PMID 24797416, 2014). "These diet-related metabolic disorders are multifaceted but characterized by peripheral insulin resistance, compensatory overproduction of insulin and increased bioavailability of insulin-like growth factor-1 (IGF-1)." (PMID 25295009, 2014). "The insulin functionality index was reduced and the insulin resistance was increased with ascending severity from the GIGT to the GDM group and with corresponding increases of total cholesterol, triglyceride and LDL-C serum concentrations." (PMID 25674108, 2014). "Type-2 diabetes (T2D) is a complex disease characterized by insulin resistance in target tissues and impaired insulin release from pancreatic beta cells." (PMID 25071836, 2014). "The buffering effect of the circulating insulin antibodies worsens insulin resistance and contributes to the increase in insulin requirements." (PMID 24711924, 2014). "Rat primary hepatocytes when cultured under metabolic overload conditions developed insulin resistance as measured in terms of failure of insulin to suppress the glucose output." (PMID 24855629, 2014). "Insulin resistance can arise from defects in insulin signaling events (typically at the levels of IRS-1 or Akt)." (PMID 24705014, 2014). "On the other hand, ROCK1 was shown to be required for insulin-induced GLUT4 translocation in cultured cells, and targeted knockout of ROCK1 caused whole body insulin resistance in mice." (PMID 24466133, 2014). "Excess hepatic glucose production is a major cause of hyperglycemia in T2D due to a diminished ability of insulin to suppress gluconeogenesis and/or glycogenolysis, namely hepatic insulin resistance." (PMID 25222566, 2014). "Under insulin resistance conditions, the antioxidant, anti-inflammatory, anti-atherogenic properties of insulin, as well as its ability to induce PI3K/NO-dependent vasodilation are attenuated, prevailing its deleterious effects." (PMID 25352918, 2014). "Serum insulin in HP− and HP+ groups was 6.97 ± 5.64 versus 10.12 ± 7.72 (P = 0.002) and insulin resistance degree was significantly higher in HP+ group (HP− = 3.160 ± 3.327 versus HP+ = 4.484 ± 3.781, P = 0.013)." (PMID 24523637, 2014). "Resistin derived its name from the original observation that it induced insulin resistance (resist-in: resist insulin) in mice and is downregulated in mature murine adipocytes cultured in the presence of insulin sensitizing drugs like thiazolidinediones." (PMID 24692844, 2014). "In particular, we assessed TG, ALT, insulin and glucose levels as markers of dyslipidaemia, liver injury and insulin resistance, respectively." (PMID 24663492, 2014). "Glucocorticoids promote hyperglycemia via a number of mechanisms: impairing insulin secretion, modulating glucose delivery to tissues, and inducing hepatic and peripheral insulin resistance." (PMID 25104497, 2014). "In a different study, strong inverse correlation was observed between ghrelin concentration and insulin levels as well as insulin resistance in middle-aged obese subjects or females with polycystic ovary syndrome." (PMID 25276131, 2014). "The resulting abnormal fat accumulation in the liver (hepatic steatosis) induces hepatic insulin resistance, impairing insulin-mediated inhibition of hepatic glucose output and increasing the risk for type 2 diabetes." (PMID 25013446, 2014). "This phosphorylation on various Ser/Thr residues is thought to inhibit insulin signaling and induce insulin resistance by blocking IRSs Tyr phosphorylation." (PMID 25580119, 2014).
Insulin resistance (continued). "Insulin resistance decreases TEG because of lower rate of glucose uptake by the tissues (Insulin-dependent glucose transport) and hence decreases the rate of glucose storage, which is an energy-requiring process." (PMID 24711817, 2014). "PTEN-specific deletion in muscle improves skeletal muscle insulin sensitivity and to protect mice from insulin resistance." (PMID 24404172, 2014). "The pathogenesis of type 2 diabetes integrates obesity, insulin resistance, and finally insulin secretion failure." (PMID 24643026, 2014). "As the miR-182 has downregulated expression that the PTEN can express higher level than usual, the upgoing expressed PTEN will attenuate the signal of insulin that come to the potential insulin resistance." (PMID 25530976, 2014). "Insulin resistance, defined as the reduced response of insulin sensitive cells to the action of insulin, has been amply demonstrated to be central to the development of T2DM and CVD." (PMID 25587486, 2014). "Consistent with induction of insulin resistance, hydrocortisone treatment significantly lowered glucose to insulin molar ratio compared to untreated controls in all groups (p<0.05, p<0.01)." (PMID 24967820, 2014). "Estrogens induce insulin sensitivity in the physiological range but can lead to insulin resistance at low (post-menopausal) and high (pregnancy) concentrations." (PMID 24524669, 2014). "High glucose significantly impaired insulin signaling in L6 cells, whereas silymarin augmented high glucose-induced insulin resistance." (PMID 24404172, 2014). "The study showed that pretreatment with gelam honey and quercetin extracts improved insulin resistance and insulin content." (PMID 24566317, 2014). "Insulin resistance can contribute to BG elevations by necessitating that beta cells secrete higher amounts of insulin to mediate sufficient glucose disposal." (PMID 24755002, 2014). "Defects of insulin signaling in obesity therefore result in insulin resistance, glucose intolerance, and decreased vascular endothelial function." (PMID 25034973, 2014). "Reports suggest that the deletion of TNF-alpha leads to increased insulin sensitivity, i.e., decreased insulin resistance." (PMID 24991532, 2014). "It has been shown that IL-10 secreted by M2 macrophages improves insulin signaling, with a protective role in obesity-induced insulin resistance." (PMID 24829560, 2014). "For example, in response to insulin resistance, the pancreatic β cell undertakes measures to proliferate and increase its output of secreted insulin." (PMID 24361012, 2014). "Our results suggest that insulin or moderate hyperinsulinemia in response to insulin resistance induces UCP-2 expression in ECs and VSMCs or in the aorta from BATIRKO MH mice respectively." (PMID 25077985, 2014). "Alternatively, the elevation of free fatty acids is a signal to increase the release of pro-inflammatory cytokines, which then activates the inflammatory signaling pathways responsible for insulin inhibition signaling and the promotion of insulin resistance." (PMID 25346723, 2014). "Insulin resistance is defined as “a relative impairment in the ability of insulin to exert its effects on glucose, protein and lipid metabolism in target tissues,” so that at physiological concentrations insulin produces a lower biologic response." (PMID 25601841, 2014). "Type 2 diabetes is characterized by insulin resistance, in which normal circulating concentrations of insulin are unable to regulate glucose levels in target tissues, such as fat, muscle, and liver." (PMID 24748202, 2014). "The defining characteristic of T2DM is peripheral insulin resistance, which occurs when cells in the body decrease their response to insulin stimulation." (PMID 25071557, 2014). "The pathogenesis of type 2 diabetes is characterised by peripheral insulin resistance and impaired insulin secretion." (PMID 25118634, 2014).
Insulin resistance (continued). "In insulin resistance, insulin secretion is too high to maintain blood glucose stability because the uptake and utilization of glucose has been reduced." (PMID 25177729, 2014). "In other words, glucose from gluconeogenesis is sufficient to stimulate sufficient secretion of insulin, which is necessary for the fat- or glucose-induced insulin resistance." (PMID 25055153, 2014). "An in vitro study showed that Res, a Sirt1 activator, enhanced insulin sensitivity in a Sirt1-dependent manner and attenuated high-fat-diet-induced insulin resistance." (PMID 25140191, 2014). "Another indicator of insulin resistance is the impaired insulin-mediated glucose uptake and metabolism by the skeletal muscle and other peripheral tissues." (PMID 24524730, 2014). "In order to further consolidate the regulatory relationship between miR-492 and resistin in insulin resistance, the expression of miR-492 and resistin in 3T3-L1 adipocytes treated with insulin were detected." (PMID 24526524, 2014). "Majority of the studies on insulin resistance typically focus on glucose metabolism, even though insulin also regulates protein synthesis and/or breakdown, especially in skeletal muscle of rodent and human whole body studies." (PMID 24997070, 2014). "These mice also display insulin resistance, which results from reduced insulin sensitivity in both skeletal muscle and white adipose tissue." (PMID 25285996, 2014). "Of importance, although there is an established link between insulin resistance and coronary artery disease (CAD), presence of HTGW was found to be associated with increased CAD risk in both normoglycemic and insulin resistant individuals." (PMID 24558974, 2014). "On the other hand, in 2 other RCTs, the presence of insulin resistance, univocally defined as a glucose-to-insulin ratio <4.5 mg/10-4, was a specific inclusion criterion." (PMID 24387273, 2014). "Notwithstanding having greater visceral adiposity, the high visceral adiposity and high fitness level group had lower parameters of insulin resistance, insulin, and HOMA-IR than did the low visceral adiposity and low fitness level group." (PMID 24454926, 2014). "Pregnancy is characterized by peripheral insulin resistance, which is compensated by an increase in insulin secretion to maintain glucose homeostasis." (PMID 24695443, 2014). "Ultimately, attention must be paid to specific defects of insulin signaling in isolated cells and to subcellular compartments affected by the increased circulating insulin that accompanies insulin resistance." (PMID 25486190, 2014). "We determined the effects of maternal diet-induced obesity on offspring adipose tissue insulin signalling and miRNA expression in the aetiology of insulin resistance in later life." (PMID 24749062, 2014). "Insulin resistance in adipose tissue leads to an impairment of insulin’s antilipolytic effect, contributing to increased flux of free fatty acids into the circulation." (PMID 25310839, 2014). "Our aim was to assess the impact of increase in homeostasis model assessment of insulin resistance (HOMA-IR) on the development of type 2 diabetes in Japanese individuals with impaired insulin secretion (IIS)." (PMID 25166121, 2014). "Studies have associated insulin resistance with disease severity of ALD in humans and in rodent models; and therapies aimed at improving insulin sensitivity improve experimental ALD." (PMID 24831094, 2014). "Mice with adipose-specific knockout of PGC1α are characterized by insulin resistance when fed a high-fat diet, emphasizing the contribution of PGC1α to maintaining insulin sensitivity." (PMID 24690289, 2014). "Age- and sex-adjusted linear regression analyses demonstrating relationships of bilirubin with thyroid hormones, components of the metabolic syndrome, insulin, insulin resistance and total cholesterol." (PMID 24595410, 2014).